CD5 (CD5 molecule)
Diseases named in the same sentence as CD5 in open-access papers (continued):
Sharing a sentence is not in itself a finding about the gene and the disease.
lymphoma (continued). "Lymphoma cells expressing CD5 (CD5+) confer inferior outcome of diffuse large B-cell lymphoma (DLBCL), especially in non–MYC/BCL2 double expressor (non-DE) patients." (PMID 36276140, 2022). "Neoplastic cells are easily recognized using a multicolor approach for their characteristic loss of CD45 and for the frequent aberrant expression of CD21, a B cell antigen, in the context of a CD3+CD5+MHC II+ lymphoma." (PMID 33969027, 2021). "Of the 23 patients with CD5+ lymphoma 16 (70%) relapsed, of whom five (31%) showed CNS progressions." (PMID 35845206, 2021). "For example, R‐Hyper‐CVAD vs. R‐CHO(E)P showed 5‐year PFS 69% vs. 40% in aaIPI 3, 72% vs. 42% in IPI 4–5, 88% vs. 38% in CNS involvement and 66% vs. 7% in CD5+ lymphoma." (PMID 35845206, 2021). "Although rare, CD5 positivity can also be present in other, mostly indolent, lymphomas, including splenic marginal zone lymphoma, hairy cell leukemia and lymphoplasmacytic lymphoma." (PMID 34898558, 2021). "Other lymphomas in the spleen rarely expressing CD5 include B-cell prolymphocytic leukemia (PLL), now a controversial entity; lymphoplasmacytic lymphoma (LPL); splenic marginal zone lymphoma (SMZL) and hairy cell leukemia (HCL)." (PMID 34898558, 2021). "A total of 195 CD5+ DLBCL patients were retrospectively recruited from nine centers in Huaihai Lymphoma Working Group." (PMID 34804942, 2021). "In terms of further histological/molecular features of DLBCL, one patient with clonally related lymphoma was a double expressor of MYC and BCL2, and one presented with CD5+ aggressive lymphoma following an initially CD5− MALT lymphoma." (PMID 31124124, 2019). "A previously reported paper disclosed that some cases of MUM1-positive-lymphoma expressed CD5 protein as well." (PMID 28086220, 2017). "Flow cytometry revealed a different population of lymphoma cells, this time positive for CD5, CD19, CD20, and CD22, with dim expression of CD45 and CD38." (PMID 27957358, 2016). "A minority (5 to 10 %) of CD3 and CD5 reactive T lymphocytes scattered between the large lymphoma B cells was documented in 17 cases." (PMID 27567676, 2016). "Our case was unique due to the de novo nature of the lymphoma and CD5 positivity of the large B cells." (PMID 27777803, 2016). "This lymphoma, consisting of CD5− and/or CD5+, is mainly characterized by clonal B-lymphocytes that are positive for CD23 and CD11c in varying percentages." (PMID 26558117, 2015). "On the other hand, CD5-positive MCLIS is associated with older age, extranodal involvement, and other lymphomas." (PMID 25478252, 2014). "The proportions of PD-L1+ and CD5+ or IgM+ cells isolated from cattle with lymphoma (11.77 ± 5.122 and 21.23 ± 6.091) were elevated compared to those of AL and BLV-negative cattle, although the differences were not statistically significant." (PMID 21943148, 2011). "N-methyl-N-nitrosourea induces murine CD4-8+ T-lymphomas that express high levelsof J11d and low levels of CD5 antigens, a phenotype characteristic of immature CD4-8+thymocytes." (PMID 1840416, 1991). "The first one was CD5−/CD10+ and large-sized (based on the forward scatter), accounting for approximately 18% of lymphoma cells, and the second subpopulation was CD5+/CD10− and small-sized (based on the forward scatter), accounting for approximately 82% of lymphoma cells." (PMID 41357579, 2025). "In the transformation process in this case, lymphoma cells lost CD5 and BCL-2 and acquired CD10." (PMID 41357579, 2025). "Other lymphoma subtypes to mention are CLL/SLL, whose normal counterpart is CD5 molecule (CD5)-positive B lymphocytes with mutated or unmutated Ig heavy variable (IGHV) genes, and LPL, which arises from post-follicular B cells that differentiate into plasma cells." (PMID 38745770, 2024). "Herein, we present a case of primary bilateral conjunctival CD5-negative MCL in a patient having no other sites affected by lymphoma and we discuss possible diagnostic pitfalls." (PMID 36661711, 2023).
lymphoma (continued). "Thus, differently from large B-cell lymphoma, the presence of >4% large CD5+ cells and an increase in their median CD5-nMFI are concerning for lymphoma and warrant further investigation." (PMID 37368760, 2023). "However, the lymphoma B-cells are positive for CD5, and CD23 but lack CD10, CD21, and cyclin D1, and this confirms the diagnosis and excludes MALT lymphoma." (PMID 37958219, 2023). "However, a small proportion (up to 5%) of BLV-infected cattle develop lymphoma originating from mono- or oligoclonal accumulation of CD5+ IgM+ B cells after a relatively long period of latency." (PMID 35632737, 2022). "Other aggressive lymphomas that may occasionally express CD5 and affect the spleen include the intravascular large B-cell lymphoma and the T-cell/histiocyte-rich B-cell lymphoma, a subtype of DLBCL." (PMID 34898558, 2021). "In this retrospective study, we retrieved 195 CD5+ DLBCL cases from the Huaihai Lymphoma Working Group (HHLWG) and analyzed the clinicopathological characteristics of CD5+ DLBCL, aiming to develop and validate a novel prognostic nomogram for individual prognosis evaluation." (PMID 34804942, 2021). "The differential diagnosis includes indolent leukemias and lymphomas that less often express CD5." (PMID 34898558, 2021). "Therefore, the staining for SOX11 in CCND1-negative CD5 expressing lymphomas is recommended to clarify the diagnosis." (PMID 34898558, 2021). "Occasionally, the clinical picture of CD5-positive, aggressive lymphomas may be dominated by splenomegaly." (PMID 34898558, 2021). "Even though we opted for the best treatment approach of upfront surgery followed byR-CHOP chemotherapy for the localized small bowel lymphoma to reduce the toxicityand improve the OS, the CD5 expression of the lymphoma dictated the prognosisirrespective of the mode of therapy." (PMID 31814435, 2019). "Expression of CD20 in lymphoma tissue could be detected in all patients by immunohistochemical analyses, while only 9% expressed CD5, 55% CD10, 9% CD30, 18% CD79a, 9% CD138, 82% BCL2, 55% BCL6 and 36% MUM1." (PMID 30340554, 2018). "The lymphoma cells were CD45+ CD20+ CD10− CD5− EBV− (by EBER)." (PMID 29850589, 2018). "There was no CD5 expression in these lymphomas, and neither was there an association with EBV infection." (PMID 22518331, 2012). "Furthermore, CD5+ B lymphoma cells produce increased levels of IL-10 relative to CD5− lymphoma cells." (PMID 20625435, 2010). "Only 30% of BLV-infected cattle develop persistent lymphocytosis (PL), a polyclonal expansion of B cells coexpressing high levels of surface IgM, myeloid (CD11b) or T-specific (CD5) markers and less than 5% will die from a fatal leukemia, lymphoma or lymphosarcoma." (PMID 15462678, 2004). "In addition, aggressive lymphomas may be dominated by splenomegaly and are occasionally positive for CD5." (PMID 34898558, 2021). "The retrospective study used a primary panel of monoclonal antibodies consisting of CD3 and CD5, CD20, CD10, CD45, PAX-5 and Ki-67 on 88 lymphoma cases." (PMID 41960458, 2026). "Based on our analysis, the most likely targets for clinical approval in disease groups such as lymphoma and multiple myeloma are CD20, CD22 (or in combination with CD19), CD38, BAFFR, CD7, and CD5." (PMID 40726984, 2025). "In regard to our case, results show a BCL2/BCL6-positive, CD10-faint, CD5/CD23-negative phenotype, suggesting a germinal center-derived lymphoma, likely DLBCL or transformed follicular lymphoma." (PMID 40062071, 2025). "T-lymphoblastic leukemia/lymphoma is characteristically positive for T cell markers, including cytoplasmic CD3 (which is lineage-defining and specific), CD5, CD7, and CD2, which can all be assessed by flow cytometric analysis." (PMID 40227608, 2025).
lymphoma (continued). "Due to insufficient sample volume for fluorescence in situ hybridization (FISH), the case was diagnosed as CD5-positive low-grade B-cell lymphoma, unclassifiable according to the 2017 revision of the World Health Organization (WHO) classification of lymphoma." (PMID 41262807, 2025). "In one study, 10.0% of cases of B-lymphoblastic leukemia/lymphoma expressed one or more T cell antigens: CD4 in 5.0% of cases, CD5 in 2.2% of cases, CD7 in 2.2% of cases, and CD2 in 0.6% of cases." (PMID 40227608, 2025). "The expression of T cell antigens, including CD2, CD4, CD5, CD7, and monocytic antigens, has also been reported in B-lymphoblastic leukemia/lymphoma." (PMID 40227608, 2025). "Co-expression of CD5 and CD10, often observed during transformation to high-grade lymphoma, suggests clonal evolution and acquired phenotypic shifts." (PMID 41146768, 2025). "IHC results indicated that the lymphoma cells strongly and diffusely expressed CD10 and BCL-2, with scattered positivity for BCL-6 and CD5, 30% positivity for C-MYC, and negativity for MUM-1." (PMID 40746899, 2025). "IVLBCL typically shows intravascular lymphoma cells (resembling DLBCL morphology) with occasional extravascular spread, expressing pan-B-cell markers, which key features include CD5+ (38%), MUM1+ (75-80%), and high Ki-67 index." (PMID 41487580, 2025). "Immunohistochemical results of the transformed lymphomas were as follows: CD10, 24% (8/33); Bcl-6, 50% (17/34); MUM1, 65% (20/31); MYC, 30% (6/20); Bcl-2, 79% (27/34); CD5, 32% (9/28); and Ki67 ≥ 60%, 53% (18/34)." (PMID 39460552, 2024). "For the differential diagnosis of other lymphomas, the immunohistochemical staining of Bcl-6 (+++), ki-67 (+++), c-myc (+), Pax-5 (++), MUM1 (+), CD5(+), and CD10 (−) was performed." (PMID 40453362, 2024). "In view of CD5 positivity in low-grade lymphoma, three differential diagnoses including SLL, mantle zone lymphoma, and CD5-positive extranodal marginal zone lymphoma were considered." (PMID 39328717, 2024). "The use of a pan-B (CD19) or pan-T (CD3, CD5 or CD7) marker allows, in a scattergram with this marker in abscissa and side scatter in ordinate, to identify the larger lymphoma cells." (PMID 38805049, 2024). "New IHC quantification rules and the joint training with other immunohistochemical biomarkers, such as CD3, CD20, CD5, BCL2, BCL6, Ki67, and MUM1, would be valuable to provide more insights into diagnosis and treatment determination of lymphoma patients." (PMID 38538739, 2024). "CD5 is highly expressed in approximately 85% of T cell malignancies, while CD30 exhibits high expression in lymphomas, specifically in anaplastic large cell lymphoma (ALCL)." (PMID 38468291, 2024). "ATA B cells can decrease CD5 in middle age and increase CD11b++CD22++ in ZAP70–CD5–, generating old age leukemia/lymphoma with autoimmune disease and control Thy-1, also ZAP70+CD5+ with CD11b+CD22+." (PMID 38570827, 2024). "Once confirmation of a hematolymphoid origin is established with CD45, the ideal IHC lymphoma work up for DLBCL includes CD3, CD20, CD5, CD10, bcl-2, bcl-6, MUM1, cyclin D1, CD30, Ki-67, and Epstein-Barr virus-encoded RNA (EBER) ISH." (PMID 37958219, 2023). "LC/MS of lymphoma tissue was performed using FFPE samples from six patients with CD5-negative DLBCL and five patients with CD5-positive DLBCL." (PMID 37705009, 2023). "For T-cell malignancies, CAR-T cells targeting T-cell makers, including CD5, CD7, and CD30, are currently being developed and have shown promising responses against T-ALL and lymphoma." (PMID 37798328, 2023). "The IgM–/– TCL1 CD19+CD5– B cell expansion is likely due to the genetic pressure of TCL1 overexpression, leading to the formation of other lymphoma/leukemia in these mice." (PMID 34813501, 2022). "Cytotoxic activity was similarly observed on T cells (CD5+ CD7+) and lymphoma cells (CD5+ CD7‒), as remaining cells had a similar T cell: lymphoma proportion after treatment." (PMID 35158792, 2022).
lymphoma (continued). "All lymphoma patients were tested for CD3, CD4, CD8, CD11a, CD5, CD21, CD34, CD79acy and MHCII expression." (PMID 34268346, 2021). "The lymphoma cells of the 5 MCL cases and 1 HG B-NHL case abnormally expressed CD5, while the 2 FL cases expressed CD10." (PMID 34879826, 2021). "A large number of preclinical trials have revealed that CAR-NK can effectively treat lymphomas and leukemias by targeting antigens such as CD19, CD20, CD7, and CD5." (PMID 34215336, 2021). "CD5 and CD10 co-expression can be seen in a subset of this lymphoma (in 38% and 13%, respectively) and almost all cases that show negative expression of CD10, are MUM1-positive." (PMID 33322508, 2020). "The lymphoma cells have a similar immunophenotype as other marginal zone lymphomas with positivity for CD20 and negativity for CD5, CD10, and CD23 in most cases by immunohistochemistry or flow cytometry." (PMID 33322508, 2020). "The addition of these antagonists improved the expansion and gene transfer efficacy of human anti-CD5 CART cells, as well as their cytotoxic capacity against CD5+ lymphoma cells." (PMID 31835562, 2019). "All these markers are essential to distinguish MZL from other types of lymphomas, such as CLL/SLL (CD5+ and CD23+), mantle cell lymphoma (CyclinD1+, CD5+, CD23−), and follicular lymphoma (CD10+ and Bcl6+)." (PMID 29740389, 2018). "Microscopic findings showed that the tumor was a hepatic MALT lymphoma, and immunohistochemical analysis revealed that the lymphoma cells were CD20+, CD79a+, BCL-2+, CD3−, and CD5−." (PMID 28353562, 2017). "It is also possible that the unique characteristics of the CD5 expression signature in antiapoptosis, proliferation, signaling, and transcription reflects the COO and the differentiation stages of the lymphoma cells." (PMID 25760242, 2015). "It has been reported that CD5+ and CD10+ lymphoma cells are present in 38 and 13% of IVLBCL cases, respectively." (PMID 24932279, 2014). "In addition, new analysis predicted lymphoma subtypes using cell-of-origin markers that hematopathologists use in the clinical routine, including CD3, CD5, CD19, CD79A, MS4A1 (CD20), MME (CD10), BCL6, IRF4 (MUM-1), BCL2, SOX11, MNDA, and FCRL4 (IRTA1)." (PMID 38745770, 2024). "In lymphoma, lymphocytes are more likely to be large and atypical, and they may lack markers CD2, CD3, CD5, and CD7." (PMID 38899272, 2024). "Lymphoma in the extra-nodal marginal zone of mucosa-associated lymphoid tissue, visible as epidermolysis bullosa and expressing B-cell markers but not CD10, CD5." (PMID 39465766, 2024). "For example, CD5 CAR-NK cells or CD7 CAR-NK cells constructed by human NK-92 cell line showed consistent, specific, and potent anti-tumor activity against a variety of T-cell leukemia and lymphoma in vitro." (PMID 39372412, 2024). "In this case, a nodal low-grade BCL with expression of CD5 and CD10 may raise the differential diagnoses of CLL/SLL, cFL, and MCL among other lymphoma types." (PMID 38535060, 2024). "Interestingly, the pattern of CD22, CD23, and FMC-7 antigens, along with the CD5 co-expression, permitted the accurate classification of all B-CLL, and CD5-/CD10-lymphoma using flow cytometry." (PMID 36624655, 2023). "Standard immunophenotyping (CD3/CD5 positivity for TCL or CD19/CD21 positivity for BCL) failed to distinguish less aggressive lymphoma from more malignant tumors." (PMID 37837297, 2023). "In our cohort of patients, the expression of CD36 was significantly elevated in CD5+ non-DE lymphoma than its CD5− counterpart, consistent with the previous findings that CD36 is one of the top variant genes that distinguished CD5+ from CD5− DLBCL." (PMID 36276140, 2022). "Taken together, in non-DE DLBCL, CD5+ lymphoma represented an increased proportion of M2 and immunosuppressive TME through reprogrammed lipid metabolism and conferred poor prognosis of patients upon R-CHOP treatment." (PMID 36276140, 2022).
lymphoma (continued). "There was no case of lymphoma observed post‐rituximab, but 1/40 (3%) patient developed CD5‐negative lymphoproliferative disorder at 5 years since her last rituximab infusion." (PMID 35666029, 2022). "On the contrary, it is expected that engagement of CD5 in lymphoma and T cells would not elicit activation of target T cells or such a downregulation mechanism." (PMID 35158792, 2022). "The lymphoma cells were positive for CD20, BCL‐6, MUM1, MYC and BCL2, and were negative for CD3, CD5 and CD10, diagnostic of DLBCL, non‐GCB type." (PMID 36467806, 2022). "By immunohistochemistry, the lymphoma cells were positive for PAX‐5, CD5 (partial/weak) (Panel E: PAX‐5/CD5 dual stain, original magnification ×400), IgD (original magnification ×400), DBA.44 (original magnification ×400), and negative for Cyclin D1, SOX11, IgG, and BRAF V600E." (PMID 35845277, 2021). "Conversely, low-grade lymphoma were characterized by the expression of T cell markers (CD3, CD5, the beta chain of the TCR, ICOS, and CD40L) and a follicular dendritic cell marker (CD23), probably reflecting the crosstalk between lymphoma cells and their environment for survival and proliferation." (PMID 32444689, 2020). "De novo CD5+ DLBCL is arare and poor prognostic subtype of lymphoma." (PMID 31814435, 2019). "CD5+ DLBCL is very rare and a poorprognostic subtype of lymphoma." (PMID 31814435, 2019). "In the univariable survival analysis, patients with CD5+ DLBCL showed significantly shorter OS (p = 0.025) and PFS (p = 0.033) than those with CD5- tumors, whereas DE lymphomas revealed inferior PFS (p = 0.036) but not OS (p = 0.234)." (PMID 31644584, 2019). "The tumor content in these samples was confirmed to have greater than 90% CD19+, CD5+ lymphoma cells by flow cytometry (data not shown)." (PMID 27713153, 2016). "CD5 positivity in DLBCL was frequently associated with lack of SSBP2 expression, a tumor suppressor protein for lymphoma and leukemia." (PMID 25760242, 2015). "Lymphoma cells usually have the following phenotype: CD2+, CD3+, CD4−, CD5−, CD7+ and CD8−." (PMID 23145171, 2012). "Although the provirus has been detected in both CD5+ and CD5- B lymphocytes from infected animals, lymphosarcoma cells appear to exhibit mainly, but not exclusively, the CD5+ B phenotype." (PMID 17362524, 2007). "The phenotype of the tumor would not be completely compatible with the less aggressive gamma/delta LGL lymphomas since the cells lacked CD5 expression nor was there neutropenia or recurrent bacterial infections." (PMID 17963509, 2007). "In contrast, MCL lymphoma showed CD 19 and CD 20 positive cell population along with CD5 positive and CD23 negative marker." (PMID 17069647, 2006). "The moderate Ki-67 (60%) and scattered c-Myc positivity indicate a somewhat aggressive clinical course, but the absence of strong MYC positivity and CD5 negativity may suggest a more favorable prognosis than double-hit or highly proliferative lymphomas." (PMID 40062071, 2025). "Neonate VH8-12/Vk21-5 CD5+ATA B cells generated old aged leukemia/lymphoma without TCL1." (PMID 38570827, 2024). "If it is not possible to discern between these two lymphomas, a diagnosis of “CD5−/CD10− low-grade B-cell lymphoma” may be sufficient." (PMID 37958219, 2023). "For example, CLL/SLL cells are positive for CD5, CD23, CD200, dim for CD20 and CD81, and negative for FMC-7; in MCL, lymphoma cells are positive for CD5, and negative for CD23; and in FL, lymphoma cells are positive for CD10 and CD20, and negative for CD34 and TdT." (PMID 34879826, 2021). "CD5-positive indolent lymphomas, however, are not included in this group, except when transformed." (PMID 34898558, 2021). "In mice, there are several models with lymphomas diagnosed histologically as SMZL that are CD5+ and may derive from peritoneal B1a cells rather than splenic MZ B cells." (PMID 23166633, 2012).